NLRP3 (NLR family pyrin domain containing 3)
Diseases named in the same sentence as NLRP3 in open-access papers (continued):
Sharing a sentence is not in itself a finding about the gene and the disease.
cancer (continued). "We argue that given the increased availability of DAMPs in the cancer TME, the NLRP3 inflammasome may mediate the propagation of the pro-inflammatory environment." (PMID 39516433, 2024). "Besides the cGAS/STING pathway, other immunomodulatory mechanisms involved in cancer include Toll-like receptor (TLRs), RIG-I, NLRP3, and CD47-SIRPα pathways." (PMID 39318624, 2024). "Knockout of NLRP3 can inhibit the proliferation, invasion, and EMT of cancer cells in vitro." (PMID 38182564, 2024). "Additionally, mitophagy and the NLRP3 inflammasome are involved in CRC progression, and their crosstalk influences cancer cell survival." (PMID 38892354, 2024). "Interestingly, our study also revealed hub genes (MEG3, MIAT, IRF1, ADAMTS9-AS2, TP63, NOD2, NOD1, NLRP3, MAGI2-AS3, and PVT1, respectively) within the pyroptosis-related ceRNA network, some of which have been well-studied in the field of cancer biology." (PMID 37511974, 2023). "An approach that targets NLRP3, specifically its ATPase activity, in the TME may offer new cancer treatment options." (PMID 37752941, 2023). "Moreover, the shift in macrophage polarization in macrophagic NLRP3-depleted mice resulted in a significant reduction in CD3+CD8+ cytotoxic T cells, the main cancer killer cells." (PMID 37077909, 2023). "Hence, our study strongly suggests that NLRP7, similar to NLRP3 and NLRP12, functions in an inflammasome-independent manner to facilitate cancer progression." (PMID 36980199, 2023). "This study reports that NLRP3 is down-regulated in cancers and identifies a novel non-immune function for NLRP3 in maintaining genome integrity through the control of ATM activation in response to DSB." (PMID 36746533, 2023). "Clinical trials directed to investigate the anti-cancer effect of specific NLRP3 inflammasome inhibitors which either target components of its canonical signaling pathway or are specific to the NLRP3 protein, have not been performed so far." (PMID 36466820, 2022). "Moreover, compared with other CGRs, ATP7B, NLRP3, and ATP7A are significantly hypomethylated in various cancers, such as BRCA, LUSC, and LUAD." (PMID 36387247, 2022). "Studies investigated the positive and negative effects that NLRP3 and its components have on specific types of cancers and gastrointestinal and gynaecological cancers seem to have a more pronounced effect." (PMID 35877745, 2022). "Although many ways of inhibiting and activating NLRP3 in cancers have been discussed before, not a lot of focus has been given to chitin and chitosan in this context." (PMID 35877745, 2022). "However, the similar responsiveness of SM and LV fibroblasts related to NLRP3 activation following IL-6 suggests that SM-derived fibroblasts could be potentially used as a tool to mirror the cardiac inflammatory NLRP3 response during cancer progression prior to cardiac damage." (PMID 35967380, 2022). "On the other hand, the release of ATP from the dying cancer cells activates P2X7 purinergic receptors on DCs and triggers the secretion of interleukin-1β(IL-1) through the activation of caspase-1, which depends on NLR family pyrin domain containing 3 (NLRP3)." (PMID 36139006, 2022). "Regulation of the XIST/SMAD2/NLRP3 signaling cascade might provide novel therapeutic interventions to circumvent chemoresistance in NSCLC and perhaps other cancer types." (PMID 36387211, 2022). "Moreover, NLRP3 has also been shown to suppress NK cell and IFN-γ mediated antitumor responses to carcinogen-induced cancers in mice." (PMID 35740272, 2022). "Pan-caner analysis indicated that NFE2L3 might promote the differentiation of Th2 cells through the IL-2/STAT5/NLRP3 signaling pathway in MPM and many other cancers." (PMID 35664314, 2022). "NLRP3 is one of the most characteristic proteins in the inflammatory bodies of the NLR protein family, which has been proved to have relation with the occurring and advancement of carcinoma." (PMID 35153782, 2022).
cancer (continued). "High NLRP3 signaling has been found in subsets of PDA-associated macrophages in both humans and mice, in which it promotes accelerated progression of PC; moreover, increased NLRP3 expression correlates with proliferation and epithelial-mesenchymal transition (EMT)-induced cancer cell invasion." (PMID 34064909, 2021). "In contrast, the NLRP3 inflammasome seems to have antitumor activity in multiple myeloma (MM) and chronic lymphocytic leukemia (CLL), in which it is expressed at lower levels in cancer patients than in healthy controls." (PMID 34064909, 2021). "We found that doxycycline inhibits LPS priming of NLRP3 and leads to early apoptosis, independent of the NLRP3 activating capacity of cancer cells." (PMID 34577552, 2021). "Altogether, these findings strongly suggest that NLRP7, similar to NLRP3 and NLRP12, may function in an inflammasome-independent manner in cancer." (PMID 34203890, 2021). "In conclusion, flavonoids can reduce several inflammatory markers such as cytokines, chemokines, inflammatory enzymes, and proteins related to migration and invasion in cancer through modulation of NF-ĸB and JAK/STAT3 signaling, AP-1 complex, and NLRP3 inflammasome." (PMID 33918290, 2021). "Since NLRP3 has been considered a more critical role in tumorigenesis and cancer progression, it has not been regarded as a potential diagnostic index and prognosis predictor." (PMID 33821998, 2021). "Therefore, the clearance of damaged mitochondria through mitophagy is considered to have a key function in regulating NLRP3 inflammasome activation and may work as a safety mechanism counteracting the hyperactivation of inflammasomes in chronic inflammation-driven cancer." (PMID 33525345, 2021). "To date, although many studies have demonstrated the role of the NLRP inflammasome in human cancers, a role of NLRP3 in HCC and its effect on NK cells have not yet been clarified." (PMID 34502191, 2021). "Collectively, the expression of NLRP3, caspase-1, GSDMD, and IL-1β protein was higher in cancer and atypical hyperplasia tissues than in benign endometrial tissues, significantly difference were observed in key pyroptotic protein caspase-1 and GSDMD (P < 0.05)." (PMID 31924176, 2020). "Taking into account cytosolic location of NLRP3 inflammasome, its ability to sense DAMPs and its dysregulation in cancer, further studies should be performed to understand the effect of intracellular HSP70 on NLRP3 inflammasome in the context of cancer." (PMID 32121660, 2020). "Autophagic cancer cell death can trigger autocrine or paracrine ATP signaling through purinergic receptors, activating NOD-, LRR-, and pyrin domain-containing protein 3 (NLRP3) inflammasome and IL-1β secretion." (PMID 32703253, 2020). "Although there is little literature on the estrogen receptors (ERalpha, ERbeta, and GPR30) for cancer and in connection with NLRP3, their impact on NLRC4 and AIM2 is not described yet." (PMID 32645874, 2020). "In summary, the present study found that NLRP3 inflammasome expression was higher in cancer tissues from LSCC patients without distant metastasis than adjacent normal tissues." (PMID 31312615, 2019). "Similarly, we observed that the expression of GCLC, NLRP3 and CD47 are downregulated in both groups of non-cancer cells treated with either LIUS or mild hyperthermia." (PMID 31355136, 2019). "In our study, we demonstrated that expression levels of NLRP3 in ccRCC cancer tissue were significantly lower than in normal kidney tissue." (PMID 30770793, 2019). "Based on the literature, we conclude that the anti-cancer properties of lentinan are not mediated by inflammasomes since lentinan did not alter AIM2 mRNA expression nor activation of NLRP3 and NLRC4 inflammasomes." (PMID 28465544, 2017). "Moreover, NLRP3 inflammasome components ASC and Caspase-1 were also highly expressed in SCCHN tissues and cancer cell lines." (PMID 28865486, 2017).
cancer (continued). "NLRP3 expression was heterogeneous in stromal, benign and cancerous prostate tissues with no distinction between the adjacent benign vs. cancer tissues." (PMID 28663562, 2017). "Given that 5-FU induces intracellular ROS production in many cancer cells, we speculated whether 5-FU would increase ROS in OSCC cells and activate NLRP3 inflammasome." (PMID 28637493, 2017). "SCCHN is an inflammation-related cancer, and the expression and function of NLRP3 inflammasome have not been clarified in SCCHN." (PMID 28865486, 2017). "Previous studies have reported that either immune or non-immune cells under certain pathologic conditions such as Sjögren's syndrome, Bechet's disease, Type 2 diabetes, rheumatoid arthritis, and various types of cancers show elevated expression of P2XR and/or NLRP3 inflammasome." (PMID 28430665, 2017). "Activation of P2X7 could increase the expression of NLRP3 and no harmful effects on cancer cell viability were noticed." (PMID 40135589, 2025). "Similarly, secretion of another NLRP3 inflammasome-dependent cytokine, IL-1β, was notably elevated in the IHGK cells (P < 0.01) and HSC-3 cells (P < 0.001), while SCC-24 A and −24B cancer cell lines showed negligible IL-1β response (P > 0.05)." (PMID 40338411, 2025). "The non-canonical activation of the NLRP3 inflammasome may play a critical role in certain cancer types." (PMID 40718836, 2025). "While its connections with inflammasome activity have not been previously delineated in malignant tumours, in the central nervous system, the priming step of NLRP3 activation may lead to NF-κB-mediated transcription of SPP1." (PMID 41148809, 2025). "Therefore, it has been proposed that CoQ0 inhibits hypoxia-induced ROS-mediated HIF-1α expression and thus attenuates the NLRP3-mediated inflammation, EMT/metastasis, and Warburg effect in HNSCC cells, which have been suggested as possible targets for cancer therapy." (PMID 38904007, 2024). "Moreover, the NLRP3 inflammasome drives the phosphorylation of protein kinase B (AKT), extracellular signal-regulated kinases 1/2 (ERK1/2), and cyclic adenosine monophosphate (cAMP) response element-binding (CREB) protein, to further induce cancer growth." (PMID 37891577, 2023). "Indeed, there is an absence of the components of the NLRP3 inflammasome, IL-18 exacerbated cancer progression and inflammatory markers." (PMID 37298187, 2023). "In addition, CRP may mediate carcinogenesis and cancer progression via activation of the FcgRs/MAPK/ERK, FcgRs/NF-κB/NLRP3, and FcgRs/IL-6/AKT/STAT3 pathways." (PMID 35847918, 2022). "ATP7B and NLRP3 showed a negative correlation in most cancers (P < 0.05)." (PMID 36387247, 2022). "Further investigation of the interplay between NF-κB and the NLRP3 inflammasome should broaden our understanding about the complex roles of NF-κB and TME in tumorigenesis, and may also lead to the development of new anti-cancer therapies." (PMID 35740272, 2022). "For instance, TRIM33 binds to DHX33 and boosts its ubiquitylation at Lys63, resulting in the activation of the NLRP3 inflammasome; TRIM33 targets β‐catenin and mediates its ubiquitylation and degradation to restrain the proliferation of various types of cancer cells." (PMID 34101965, 2021). "Instead of targeting MDSC’s directly through CD33, inhibitors that specifically target TLR signaling and their downstream effectors, IRAK and the NLRP3 inflammasome, may provide another avenue to disrupt pyroptosis-mediated cell death of HSPC’s and β-catenin-induced proliferation of cancer cells." (PMID 34521810, 2021). "And, strictly speaking, as knockdown of MEG3 only partly abolished the activation of DDP-induced NLRP3/caspase-1/GSDMD pathway and anti-cancer functions in MDA-MB-231 cells, MEG3 may partially mediated the pyroptotic signaling upon DDP treatment in this type of TNBC cell line." (PMID 34326697, 2021).
cancer (continued). "The pyrin domain-containing multiprotein complex NLRP3 inflammasome, consisting of the NLRP3 protein, ASC adaptor, and procaspase-1, plays a vital role in the pathophysiology of several inflammatory disorders, including neurological and metabolic disorders, chronic inflammatory diseases, and cancer." (PMID 34684819, 2021). "Moreover, TAT-FADD targets NF-κB signaling to suppress the expression of anti-apoptotic genes Bcl2, cIAPs, RIP1, and cFLIPL in cancer cells, and TAT-FADD abolishes NLRP3 inflammasome transcriptional priming and processing of IL-1β in colon carcinoma HCT116 cells." (PMID 32961826, 2020). "Due to the flagellin-induced IL6, which is known to inhibit apoptosis in many cancer cell types, we measured the effects of flagellin on the caspase-1 activity of the C26 cells together with either TLR5 antagonist or genipin, which inhibits NLRP3-mediated inflammasome activation." (PMID 31731747, 2019). "Based on the existing literatures, we find (a) coptisine exerted potential to be an anti‐cancer, anti‐inflammatory, CAD ameliorating or anti‐bacterial drug through regulating the signalling transduction of pathways such as NF‐κB, MAPK, PI3K/Akt, NLRP3 inflammasome, RANKL/RANK and Beclin 1/Sirt1." (PMID 31622015, 2019). "Moreover, in a mice model, NLRP3 deletion inhibited lung tumorigenesis by reducing the levels of IL-1β, whereas its activation upregulated signaling pathways like PI3K-AKT, Erk1/2, and STAT3, which altogether contributed to increased proliferation and cancer metastasis." (PMID 41376623, 2025). "However, because inhibiting NLRP3 with gli fails to suppress cancer cell growth and the metastatic phenotype, there may be drawbacks to its use in CRC." (PMID 38543085, 2024). "Considering OLP as an OPMD with the potential to progress into OSCC, the significantly increased expression of both Gal-3 and the NLRP3 inflammasome may potentially indicate a trend towards the malignant transformation of OLP, given the well-established connection between inflammation and cancer." (PMID 38172822, 2024). "Triggered by a hypoxic microenvironment, highly expressed ERRα could bind to the promoter of NLRP3 and inhibit caspase-1/GSDMD signaling, which reduced inflammasome activation and increased pyroptosis resistance, thereby resulting in the resistance of cancer cells to cisplatin." (PMID 37864196, 2023). "Additionally, although inflammasome targeting is used as a therapeutic approach in many diseases, our study showed that inhibition of NLRP3 may not be the best approach for the treatment of some cancers." (PMID 33613529, 2020). "However, their potential in NLRP3-related cancers has not been investigated yet." (PMID 32733479, 2020). "And this study provided evidence that high NLRP3 inflammasome (NLRP3/IL-18/IL-1β/ASC) expression in LSCC cancer tissues suggests a poor prognosis of LSCC without distant metastasis in a Chinese population, which may help identify a new prognosis factor for LSCC." (PMID 31312615, 2019). "Independent of the cancer type, there is a significant positive correlation between FLT3 and NLRP3 expression." (PMID 39875995, 2025). "Once NLRP3 is absent, the expression of P2X7R will be promoted, which contributes to cancer growth as a negative feedback loop." (PMID 35964092, 2022). "Despite the development of potent and specific NLRP3 inhibitors, such as MCC95090,91, there are currently no clinical trials investigating their use in cancer patients." (PMID 33116132, 2020). "Importantly, only a few NLRP3-targeting compounds, such as DFV890, have entered early-stage clinical trials, and none have yet progressed to cancer studies." (PMID 41560727, 2025).
cancer (continued). "Mice lacking NLRP3, caspase-1, and ASC adaptors are protected from cancer progression." (PMID 37715239, 2023). "To determine whether NLRP3 inflamasome was associated with human HNSCC, we examined their expression by immunohistochemistry and found that NLRP3, Caspase-1, ASC, IL-18 were highly expressed in the cytoplasm of cancer cells, and the expression of them was negative or low in the normal mucosa." (PMID 28865486, 2017).